PTX3 (pentraxin 3)
Diseases named in the same sentence as PTX3 in open-access papers (continued):
Sharing a sentence is not in itself a finding about the gene and the disease.
infection (continued). "Experimental and clinical data indicate that PTX3 rises rapidly within 6–8 h of inflammatory stimulation and typically declines over days following resolution of the triggering event, although persistence may occur in chronic or slowly resolving infections." (PMID 41471254, 2025). "Ptx3 deficiency did not affect the local phagocytosis by recruited neutrophils and, given the low efficiency of the binding to pneumococcus, pre-opsonization of the inoculum did not modify the kinetic of infection." (PMID 37222419, 2023). "As opposed to the synovial protein, the plasmatic concentration of PTX3 had poor diagnostic value, likely due to this long pentraxin being mainly synthesized in loco at sites of infection, unlike the short pentraxin CRP that is systemically produced by the liver in response to IL-6." (PMID 36769703, 2023). "In addition, PTX3 deficiency was associated with a higher amount of MPO (P = 0.004 at 44h after infection) and a higher percentage of neutrophils in the lung (P = 0.04 at 44 hours after infection)." (PMID 34093560, 2021). "Finally, we assessed the contribution of complement in PTX3-mediated activity in K. pneumoniae infection, by comparing the survival of wild-type and Ptx3-/- mice to C3-/- and Ptx3-/-/C3-/- mice after intranasal infection." (PMID 34093560, 2021). "That being said, we cannot exclude the possibility that all three bacterial species may be capable of evading PTX3-mediated amplification of innate immune responses, with PTX3 production representing a futile host response to amplify complement-directed lysis and limit infection." (PMID 31492148, 2019). "Thus, we reasoned that PTX3 plasma level measurements could be somewhat affected by ongoing infections." (PMID 27893415, 2016). "We then evaluated whether PTX3 can exert a protective role toward infection with MenB." (PMID 25786110, 2015). "Next, we examined whether PTX3 colocalizes with RRV during infection." (PMID 25695775, 2015). "As a matter of caution, PTX3 is not a general mechanism to guard against all pathogenic infections." (PMID 23755050, 2013). "Hence, the genes Ccl2, Ch25 h, Ifit3, Il1rn, Il6, Parp14, Ptx3, and Socs3 can be defined as a common core of genes expressed early in response to local infection and inflammation caused by Gram-negative stimuli." (PMID 21338499, 2011). "Since S100A12 and PTX3 display microbial growth inhibition and binding properties, respectively, they could provide a new class of natural anti-microbial agents that could assist defense of the mammary gland against chronic and subclinical infections." (PMID 18513449, 2008). "PTX3 differs structurally and functionally from short pentraxins such as C-reactive protein (CRP), being synthesized locally at sites of infection by monocytes, macrophages, endothelial, and epithelial cells." (PMID 41471254, 2025). "PTX3, part of the long pentraxin subfamily and inducible by IL-1 or TNF, plays a role in infection defense, tissue repair, and managing inflammation in cancer." (PMID 38895120, 2024). "All the data above suggested that PTX3 can elicit strong immune responses and facilitate bacterial clearance during the SS2 infection, suggesting that PTX3 protein can be used as an efficient therapeutic agent or a vaccine adjuvant." (PMID 36977278, 2023). "Thus, we speculated whether PTX3 is related to CPS2 in the process of resisting SS2 infection." (PMID 36977278, 2023). "(D) Bacterial load was analyzed in lungs collected 36 hr post-infection from WT, Ptx3−/− and Ptx3−/− mice treated intraperitoneally with recombinant PTX3 (10 μg/100 μl) before the infection and 24 hr post-infection (n = 18–23)." (PMID 37222419, 2023). "Its secretion by immune system cells such as DC and PMN in response to infection as well as its ability to serve as humoral PRR, binding to different pathogens, makes PTX3 a dominant player in innate immunity." (PMID 35956001, 2022).
infection (continued). "Mtb also aggressively stirs up the assembly of pentraxin-3 (PTX-3), a 42 KDa soluble PRR involved in acute immune responses towards infection." (PMID 36298605, 2022). "A comparison of ROC curves for PTX3 and PCT concentrations revealed similar sensitivity and specificity in the prediction of infection in neonates." (PMID 34307663, 2021). "In the serious infection group, all cases exhibited a high concentration of CRP, as well as PTX3 concentration." (PMID 31147578, 2019). "Overall, lower expression of IL17, IL22, PTX3, and heterophil attracting cytokines, such as CXCL8 and VCAM1 in our data suggests a dampened innate immune response post APEC O2-GFP infection." (PMID 31998322, 2019). "By binding to CMV through sialic acids expressed on its glyosidic moiety, PTX3 was demonstrated to be effective in averting CMV infection and reactivation in selected in vivo and in vitro models of infection." (PMID 30766534, 2019). "Such high relative PTX3 concentration to neutrophil count ratios were found in only a few cases of the ACS and infection groups." (PMID 31147578, 2019). "It should be noted that the ROC-AUC for 180-day mortality was low but comparable to a previous study investigating PTX3, PCT and CRP in emergency room patients with suspected infection." (PMID 26880104, 2016). "At 30 hpi, MEC express genes encoding different acute phase proteins, including SAA3, SERPINA1 and PTX3 and factors, such as S100A12, that contribute directly to fighting the infection." (PMID 24521038, 2014). "We previously reported that long pentraxin 3 (PTX3), a pattern recognition molecule involved in inflammation, tissue repair, and wound healing, is a negative regulator of immunity in primary Leishmania major infection." (PMID 41743710, 2026). "Pentraxin-3 (PTX-3) is a pattern recognition molecule in the same protein family as C-reactive protein (CRP) and is produced in various extrahepatic tissues and blood cells in response to inflammation and infection." (PMID 40008348, 2025). "Pentraxin 3 (PTX3), a key component of humoral immunity, is rapidly produced and released by macrophages, dendritic cells (DC), fibroblasts, and activated endothelial cells at sites of infection or inflammation." (PMID 40313930, 2025). "Besides IL-6, other cytokines of the acute inflammatory response including IFN-β, Pentraxin 3 (PTX3), IFN-γ, and IFN-λ2/3 were shown to be elevated during Long COVID, up to 8 months post-infection." (PMID 39849406, 2025). "In fact, inhibition of ADA by EHNA after 3 h of infection with TcdA in the ileum of mice reduces tissue damage, neutrophil infiltration, and the level of the pro-inflammatory cytokines TNF-α, IL-1β, as well as the expression of NOS2, NF-κB and PTX3." (PMID 40646589, 2025). "Unlike CRP, PTX3 is generated at the infection site by a variety of cell types, such as monocytes and neutrophils, in response to inflammatory triggers (such as cytokines or microbial moieties)." (PMID 39294659, 2024). "Following infection with M. bejeranoi, proteins related to the fish immune system were increased, most prominently Scavenger Receptor Cysteine-Rich (SRCR) domain-containing protein (m130/cd163) (fold change 6.12) and pentraxin 3 (fold change 4.38)." (PMID 38891869, 2024). "Pentraxin 3 (PTX3), a soluble pattern recognition molecule belonging to the humoral innate immune system, is primarily produced by fibroblasts, phagocytes, and endothelial cells in response to infection or tissue injury." (PMID 38136144, 2023). "When Ptx3−/− mice were infected with S. pneumoniae (5 × 104 CFU), a significant increase of the bacterial load in the lung was observed during the invasive phase of infection (i.e. 36 hr post-infection), compared to WT mice." (PMID 37222419, 2023). "Moreover, studies have demonstrated increased expression of PTX3 in TLR4-dependent manner and it exhibits opsonizing activity via TLR4 pathway during infection." (PMID 36741398, 2022).
infection (continued). "PTX3 is a soluble pattern recognition molecule (PRM) belonging to the humoral innate immune system, rapidly produced at inflammatory sites by phagocytes and stromal cells in response to infection or tissue injury." (PMID 34276664, 2021). "As opposed to CRP and SAP, PTX3 is rapidly synthesized and secreted at sites of infection/inflammation by a variety of immune and non-immune cells in response to TLR engagement, microbial moieties, and inflammatory cytokines." (PMID 34868070, 2021). "In our study, treatment with recombinant PTX3 decreased the systemic spread of the infection and mortality in Ptx3-/- mice, but did not ameliorate the control of the infection in wild-type mice." (PMID 34093560, 2021). "Thus, PTX3 has a different kinetics of production and different patterns of recognized ligands from CRP, a much more widely used biomarker of inflammation and infection." (PMID 31057548, 2019). "Lastly, the patients with NSTI had a significantly higher baseline PTX3 level compared with control patients without infection (52.4 (IQR, 17.7–172.2) versus 2.9 (IQR, 2.0–4.5) ng/mL, p < 0.0001)." (PMID 26880104, 2016). "Specifically, the median PTX3 level in infection-free “no-GvHD” patients was 12.73 ng/ml (range = 3.80-49.64 ng/ml), significantly lower than that of GvHD patients (p = 0.0013)." (PMID 27893415, 2016). "Having demonstrated the effect of PTX3 on the induction of soluble inflammatory mediators during acute RRV infection, we next investigated the effect of PTX3 on leukocyte recruitment during in vivo infection." (PMID 25695775, 2015). "In addition to elevated PTX3 expression in alphavirus-infected patients, we also report abundant expression of PTX3 in serum and spleen of RRV-infected mice at the early stage of infection." (PMID 25695775, 2015). "The PTX3 levels are very low in serum and tissue compartments of normal subjects but are rapidly increased in response to inflammation triggered by infections, autoimmunity, or mechanical stress." (PMID 26644796, 2015). "High PTX3 and PCT levels were shown here to be independent predictors of case fatality on day 28 when plasma samples were taken on admission together with blood cultures from patients with suspected infection." (PMID 23341967, 2013). "Infection due to Listeria monocytogenes and Salmonella typhimurium is neither controlled nor exaggerated by PTX3 directly or indirectly." (PMID 23755050, 2013). "Several studies have shown the usefulness of PTX3 and CRP in assessing the severity of infection." (PMID 23341967, 2013). "Furthermore, plasma and bronchoalveolar lavage fluid (BALF) PTX3 levels were significantly higher in IPA patients compared to those with other types of pathogen infections or without infection." (PMID 39878524, 2025). "Also, a strong and positive correlation emerged between the synovial levels of IL-1β and PTX3 (Spearman r = 0.67, p = 0.004) that was lost in the absence of infection." (PMID 38790226, 2024). "Both PTX3 and sMR plasma concentrations were 1.7-fold increased in non-survivors when compared to survivors (p = 0.0388 and p = 0.0070, respectively) in the first few days after infection or symptom onset (day 0)." (PMID 39027374, 2024). "High levels of acute phase proteins (CRP, pentraxin-3 (PTX-3), procalcitonin, presepsin) in patients with MI-CS at day 1 after admission to hospital were associated with increased 3-month mortality regardless of the presence or absence of secondary infection." (PMID 39335587, 2024). "Unlike the short pentraxin C reactive protein (CRP), whose expression is mostly confined to the liver, PTX3 is made by several immune and non-immune cells at sites of infection and inflammation, where it intercepts fundamental aspects of infection immunity, inflammation, and tissue remodeling." (PMID 37885881, 2023).
infection (continued). "The study’s results showed that PTX3 facilitated the phagocytosis of macrophage Ana-1 against SS2 strain HA9801, and contributed to inflammatory cell recruitment and cytokine IL-6 release in the mouse air pouch; thus, it was conductive to bacterial clearance during the SS2 infection." (PMID 36977278, 2023). "In conclusion, it is important to consider pregnancy-specific reference values as elevations of CRP and PTX3 during the later phase may occur in absence of infection." (PMID 34408755, 2021). "Tnf and Il1b, which were found to be up-regulated in this study, could promote the transcription and expression of Ptx3, a humoral pattern recognition receptor and nonredundant component of humoral innate immunity for anti-infection." (PMID 28899359, 2017). "In addition, serum PTX3 levels did not differentiate an infection group from a flare group in patients with systemic lupus erythematous (SLE)." (PMID 23383162, 2013). "Thus, the circulating PTX3 level increases non-specifically in various infections and inflammatory disorders." (PMID 23248627, 2012). "However, to the best of our knowledge no study has investigated the prognostic value of PTX3 in a cohort of patients with bacteremic infection." (PMID 21423699, 2011). "At the common infection dose of 1 × 105 bacteria for cows 1419, 1490 and 1592, there was 5.2, 36.5 and 49.1 fold up-regulation of S100A12 expression and 11.1, 9.9 and 19 fold up-regulation of PTX3 expression, compared to the intra-animal controls, respectively (all P < 0.01)." (PMID 18513449, 2008). "PTX3 could not be detected in milk from the pre-infection udders or the post-infection control udders." (PMID 18513449, 2008). "PTX3 is expressed by various hematopoietic and non-hematopoietic cells in response to microbial moieties and inflammatory cytokines (i.e IL-1β and TNF), and it has been associated with the control of various infections by promoting different anti-microbial mechanisms." (PMID 37222419, 2023). "Therefore, the kinetics of PTX3 appear more favorable than other acute phase markers in pediatric cardiac surgery patients in the early postoperative period; however, our results concern children without postoperative infections." (PMID 35989325, 2022). "Thus, the non-specific role of PTX-3 in infection and inflammation might preclude the protein's utility as a general biomarker to distinguish KD patients from other febrile children." (PMID 32670996, 2020). "At a local level of infection, extracellular Shigella that are no longer protected by the host cell cytoplasm, can be targeted by the complement system and easily internalized by macrophages, thus improving the bacterial clearance by the tissues as we observed in lungs of PTX3-treated mice." (PMID 30532257, 2018). "Although Ptx3 serum level is considered a nonspecific feature with respect to invading pathogens, Ptx3 monitoring in BALF, i.e., in the early and primary site of infection, produces interesting results." (PMID 36830296, 2023). "A comparison of receiver operating characteristic curves for PTX3, PCT, and CRP concentrations did not demonstrate any statistically significant differences in the prediction of infection in newborns (p = 0.40)." (PMID 34307663, 2021). "Collectively, these data demonstrate that the absence of PTX3 results in delayed inflammatory responses in quadricep muscles of RRV-infected mice, as well as enhanced production of these immune mediators in the latter stages of infection." (PMID 25695775, 2015). "In sepsis, PTX3 was reported to be superior to the classical biomarkers CRP and procalcitonin (PCT), probably due to the fact that it is locally produced at the site of tissue damage or infection, rather than relying on other molecules to trigger the synthesis of body organs." (PMID 40299501, 2025).
cancer (132 papers, 2011 to 2026). A tumor composed of atypical neoplastic, often pleomorphic cells that invade other tissues. "PTX3, a member of the pentraxin family, is well-known for its involvement in immune responses and has been linked to various cancers." (PMID 40656950, 2025). "With the growing recognition that inflammation and tissue repair are closely linked to tumorigenesis, the relationship between PTX3 and cancer has been the subject of extensive research." (PMID 41479916, 2025). "Remarkably, PTX3 has exhibited the highest sensitivity and specificity among biomarkers of cancer-associated inflammation." (PMID 39594709, 2024). "PTX3 demonstrates considerable potential as both a diagnostic biomarker and therapeutic target in cancer." (PMID 39594709, 2024). "Studies were included if they assessed the association between PTX3 protein expression and overall survival (OS) in cancer patients." (PMID 39594709, 2024). "Higher PTX3 expression has been particularly associated with more aggressive cancer phenotypes, including increased cell migration, invasion, and metastasis." (PMID 39594709, 2024). "Increased PTX3 serum levels have been found in patients with various types of cancer compared to healthy controls, and high serum levels of PTX3 have also been associated with a worse prognosis." (PMID 38542446, 2024). "Studies have consistently shown elevated gene expression or serum levels of PTX3 in cancer patients, highlighting its diagnostic utility across various malignancies." (PMID 39594709, 2024). "To better understand its impact, we conducted a meta-analysis of the clinical data to assess how high levels of PTX3 are linked to cancer outcomes." (PMID 39594709, 2024). "Several inflammatory biomarkers demonstrate diagnostic and prognostic value in various cancers, yet PTX3 has shown superiority over other inflammation-related biomarkers in cancer prognosis." (PMID 39594709, 2024). "The results showed that elevated PTX3 expression is associated with poorer survival in cancer patients, with a pooled hazard ratio of 1.89." (PMID 39594709, 2024). "Increased levels of gastric cancer associated PTX3 promote macrophage recruitment and cancer-related inflammation." (PMID 35739102, 2022). "Accumulating evidence in conjunction with our current results indicates that PTX3 is associated with or contributes to cancer malignancies." (PMID 35090088, 2022). "In this review, we present evidence for the correlation between PTX-3 and cancer, focusing on the underlying mechanisms of action." (PMID 36499628, 2022). "The involvement of PTX-3 in complement cascade activation as a pathogenic pathway and its further insidious correlation with various types of cancers has been widely studied in the past years and results seem promising." (PMID 36499628, 2022). "Methylation of the PTX3 promoter and loss of CEBPD expression typically result in attenuated PTX3 expression in cancer cells." (PMID 35090088, 2022). "The underlying mechanisms of PTX3 in cancers have been explored previously, including macrophage infiltration, cytokine production, angiogenesis, and genetic instability." (PMID 36139597, 2022). "We clarified the expression patterns, genetic alterations, prognostic significance, and the underlying mechanisms of the COVID-19 biomarker PTX3 across TCGA cancers." (PMID 36139597, 2022). "PTX3 deficiency has been reported to potentially raise the risk of cancer development by deregulating tumoral inflammation in various models of skin carcinogenesis." (PMID 34048179, 2021). "As far as we know, few studies have revealed a significant association between PTX3 genetic variants and cancer development." (PMID 33967610, 2021). "Another detected modulator of ECM and better known as protein-related with acute-phase protein, Pentraxin-3, has been implicated in cancer progression, by modulating angiogenesis, metastatic spread, and cancer immune response." (PMID 34283046, 2021).